ENSG00000252693
Synonyms: LOC124900500
Gene: Small nucleolar RNA gene on chromosome X (124,197,743 to 124,197,849, forward strand). Ensembl gene ENSG00000252693.
Gene Ontology:
Biological process: RNA processing
Cellular component: nucleolus
Homologues: Paralogues in human: SNORA40B (91% identical), SNORA40 (88% identical), SNORA40C (86% identical).